MIR6875 (microRNA 6875)
Synonyms: hsa-mir-6875
Gene: MicroRNA gene on chromosome 7 (100,868,036 to 100,868,107, forward strand). Ensembl gene ENSG00000283821.
Homologues: Orthologues: chimpanzee MIR6875 (100% identical).